RN7SL8P (RNA, 7SL, cytoplasmic 8, pseudogene)
Synonyms: 7L63; formerly RN7SLP5; RN7SL433P
Gene: Miscellaneous RNA gene on chromosome 7 (104,911,928 to 104,912,193, forward strand). Ensembl gene ENSG00000243352.
Homologues: Orthologues: chimpanzee Metazoa_SRP (97% identical). Paralogues in human: RN7SL2 (79% identical), RN7SL1 (79% identical), RN7SL3 (79% identical), RN7SL5P (77% identical), RN7SL278P (76% identical), RN7SL444P (75% identical), RN7SL448P (75% identical), RN7SL4P (75% identical), RN7SL732P (75% identical), RN7SL769P (75% identical), RN7SL118P (75% identical), RN7SL126P (75% identical), and 705 more.